ULBP3 (UL16 binding protein 3)
Diseases named in the same sentence as ULBP3 in open-access papers (continued):
Sharing a sentence is not in itself a finding about the gene and the disease.
tumor (continued). "In future studies, it will be important to determine whether the level of serum ULBP3 in cancer patients correlates with the progression and outcome of malignancies, in order to assess ULBP3 as a potential tumor marker." (PMID 25138242, 2014). "We found that ULBP3 was overexpressed on tumor cell lines and tumor tissues." (PMID 25138242, 2014). "Given that tumor cells generally expressed surface ULBP3 and sULBP3, an anti-ULBP3 antibody could contribute to the activity of NK cells against ULBP3-expressing tumor cells." (PMID 25138242, 2014). "Notably, protein degradation inhibitors failed to rescue the expression of MICA, MICB, and ULBP3, indicating that the reduced protein levels of MICA, MICB, and ULBP3 in the infected tumor cells were due to the impaired translation of these ligands, and not due to increased protein degradation." (PMID 37753084, 2023). "We examined the surface expression of MICA/B, ULBP1, ULBP2/5/6 and ULBP3 on SKOV-3, BT-474 and MCF-7 tumor cells growing in 3D culture after spheroid dissociation." (PMID 39457710, 2024). "In tumor cells, ligands of ULBP1, ULBP2/5/6, ULBP3, ULBP4, and MICA/B can bind to NKG2D receptors among tumor-activating receptors of NK cells." (PMID 39339179, 2024). "The protein expression pattern of MICA/B, ULBP1, ULBP3, and ULBP4 between paired tumor and adjacent tissues was consistent with that in mRNA levels of the TCGA‐LIHC dataset." (PMID 36210637, 2023). "Our differential expression analysis results showed that ULBP1, ULBP2, ULBP3, and RAET1L had significant differential expression in COAD tumor and adjacent normal tissues." (PMID 33909599, 2021). "The tumour secretes factors such as soluble MICA, MICB, and vesicles containing ULBP3, all of which impair NK cell cytotoxic ability, facilitating immune evasion." (PMID 28668076, 2017). "UL16-binding protein 3 (ULBP3), an NKG2D ligand, is overexpressed on certain epithelial tumor cells." (PMID 25138242, 2014). "The lysis efficiency of the tumor cell lines CD133−SW620 and 7721 at an E:T ratio of 10:1 was enhanced in the presence of anti-ULBP3 monoclonal antibody (B2-F1-F1)." (PMID 25138242, 2014). "Intriguingly, the addition of an anti-ULBP3 antibody prepared in our laboratory triggered ULBP3-mediated ADCC and increased NK cytotoxicity against ULBP3-expressing tumor cells, suggesting the antibody has immunotherapeutic value for cancer treatment." (PMID 25138242, 2014). "The HTB-186 tumor cell line expressed the highest levels of HLA class I, MICA, ULBP-2, ULBP-3 and the lowest NKG2DLs/HLA class I ratio." (PMID 23626949, 2013). "Strong expression of Vδ1+ T cell target NKG2D ligands (NKG2DL) ULBP-2 and ULBP-3 and moderate expression of ULBP-1 was noted on both tumor cell lines." (PMID 23950874, 2013). "Formalin-fixed paraffin-embedded tumor tissue was immunohistochemically stained with antibodies directed against MIC-A/MIC-B (MIC-AB), ULBP-1, ULBP-2, ULBP-3, ULBP-4, and ULBP-5." (PMID 22257486, 2012). "The signature based on MICA, ULBP3, and ULBP5 could predict HCC recurrence in three independent cohorts, which was related to the levels of NK‐cell infiltration in HCC tumor tissues." (PMID 36210637, 2023). "They analyzed GSC derived from primary tumor samples by mass cytometry, and the GSC expressed normal levels of NK cell activation receptor ligands (ULBP2, ULBP3, VIM) and upregulated levels of NK cell inhibitory receptor ligands (HLA-A, HLA-B, HLA-C, HLA-E, HLA-G, PCNA) compared with non-GSC." (PMID 34638384, 2021). "To determine whether tumor cells release sULBP3, we used a time-resolved fluoroimmunoassay (TRFIA) with a Eu3+-labeled anti-ULBP3 monoclonal antibody." (PMID 25138242, 2014). "When analyzing tumor tissue samples from cancer patients, we found a negative correlation between the percentage of infiltrating NK cells and the level of ULBP3 expression." (PMID 25138242, 2014).
tumor (continued). "In addition to PD-L1 upregulation, suppression of NK group 2D (NKG2D)-activating ligands (including ULBP1, ULBP2, ULBP3, MHC class I chain-related molecules A and B, MICA and MICB) may represent another way of tumor escape from NKCC." (PMID 34830209, 2021). "To explore this hypothesis, we investigated the expression of MICA/B, ULBP1, ULBP2, ULBP3, RAET1E, and RAET1G in normal cervical epithelium and cervical neoplasia in a large series of formalin-fixed, paraffin-embedded tumor samples made by using high-throughput tissue microarray (TMA) technology." (PMID 25510288, 2014). "MICA/B and ULBP4 were moderately (IHC score: 4–6) or highly (IHC score: 7–12) expressed in more than 2/3 HCC tumor samples, whereas ULBP1, ULBP3, and UBP2/5/6 were not (IHC score: 0) or lowly (IHC score: 1–3) expressed in more than 2/3 HCC tumor samples." (PMID 36210637, 2023). "Here we show, for the first time, that human tumor cells lost their surface expression of ULBP2, but not ULBP1 and ULBP3, during NK cell-mediated cytolysis." (PMID 24614922, 2014).
cancer (12 papers, 2011 to 2026). A tumor composed of atypical neoplastic, often pleomorphic cells that invade other tissues. "This suggests that the variants present in the associated signals may alter not only RAET1L expression but also ULBP1, ULBP2, and ULBP3 and affect the risk of cancer and immune diseases." (PMID 40116579, 2025). "Collectively, these results demonstrate that EHMT2-mediated TGF-β1 upregulation in an autocrine manner, inhibits NKG2D ligands (MICB and ULBP3) on cancer cells and, in a paracrine manner, suppresses the cytotoxic ability of NK cells and their migration." (PMID 41366520, 2026). "TGF-β1 in an autocrine manner suppressed activating ligands MICB and ULBP3 on cancer cells, of which MICB was necessary for NK cell-induced cytotoxicity." (PMID 41366520, 2026). "EHMT2 loss increased AZGP1 and decreased TGF-β1 levels, resulting in the autocrine elevation of NKG2D ligands MICB and ULBP3, chemokines in cancer cells, and the paracrine stimulation of NK cell function." (PMID 41366520, 2026). "Immunohistochemistry results also showed that ULBP3 expression was upregulated in colorectal (n = 5), liver (n = 3), lung (n = 5), and gastric (n = 5) cancer tissue." (PMID 25138242, 2014). "However, the regulatory function of ULBP3 in NK cells and its significance in cancer patients are largely unknown." (PMID 25138242, 2014). "Thus, ULBP3 is a potential therapeutic target for improving the immune response against cancer." (PMID 25138242, 2014). "Specifically, the inhibition of EHMT2 and TGF-β1 resulted in increased expression of NKG2D ligands (ULBP3 and MICB) on cancer cells in an autocrine manner, resulting in enhanced NK cell-mediated cytotoxicity." (PMID 41366520, 2026). "DAC also upregulates UL16-binding proteins 2 and 3 (i.e., ULBP2 and ULBP3), another group of NKG2D ligands that are expressed in many cancers and in stressed/damaged tissues 18–20." (PMID 33846331, 2021). "However, NKG2D ligands, ULBP3 and MICA/B, showed similar expression levels in cancer and normal cells." (PMID 41050660, 2025). "MICB, ULBP-1, and ULBP-2, but not MICA and ULBP-3, were detected in sera from most patients starting HD, and it was difficult to discriminate between the presence and absence of a cancer history using the levels of soluble NKG2DLs." (PMID 37674990, 2022). "Meanwhile, very few cancer tissues expressed ULBP1 and ULBP3." (PMID 31288857, 2019). "Serum from cancer patients, but not from healthy donors, contained elevated levels of soluble ULBP3 (sULBP3)." (PMID 25138242, 2014).
infection (10 papers, 2009 to 2025). The state of being infected such as from the introduction of a foreign agent such as serum, vaccine, antigenic substance or organism. "As MICB, ULBP1 and ULBP3 are downregulated following infection, we aimed to see if infected cells are less susceptible to NKG2D-dependent recognition by NK cells." (PMID 34721381, 2021). "BKPyV miRNAs contribute to latency by targeting early viral mRNA to suppress replication and by downregulating UL16 binding protein 3 (ULBP3) expression during infection, enabling the virus to evade NKG2D-mediated immune recognition and elimination." (PMID 40137721, 2025). "ULBP2 expression was reduced at 24 hrs post-infection, and ULBP3 expression was reduced as early as 12 hrs post-infection." (PMID 37753084, 2023). "In this study, we identify two HHV-6A encoded immunoevasins, U20 and U21, which suppress the expression of the NKG2D ligands ULBP1 and ULBP3, respectively, during infection." (PMID 34721381, 2021). "No significant change in ULBP1 or PVR surface expression was detected and a slight increase in ULBP3 levels during infection with both strains was noticed." (PMID 28819195, 2017). "ULBP2 and ULBP3 were downregulated at earlier stages of infection." (PMID 37753084, 2023). "Intracellular protein levels of MICA, MICB, ULBP2, and ULBP3 were tested 48 hrs post-infection." (PMID 37753084, 2023). "ULBP3 levels were dramatically decreased following infection in J-Jhan cells." (PMID 34721381, 2021). "Interestingly, we observed a strong decrease of all MICB, ULBP1 and ULBP3 total protein following infection with HHV-6A (quantified in the bar diagram) indicating that there is no intracellular retention, but actual reduction in overall protein levels." (PMID 34721381, 2021). "Importantly, in presence of sgRNAs targeting U20, ULBP1 levels were significantly restored after infection and in presence of sgRNAs targeting U21, ULBP3 levels." (PMID 34721381, 2021). "MICA, MICB, ULBP2, and ULBP3 were upregulated following infection with both HMPV/WT and HMPV/ΔG." (PMID 32698530, 2020). "Infection with WT DHIV only induced a 1.5-fold increase in the expression ULBP-3, MIC-A and MIC-B." (PMID 19798433, 2009). "We recently studied HHV-6B, a closely related β-herpesvirus, which targets ULBP1, ULBP3 and MICB during infection." (PMID 34721381, 2021). "We demonstrate that the infected cells respond to the infection and that, upon infection, the mRNA and the total protein amount of MICA, MICB, ULBP2, and ULBP3 are upregulated." (PMID 32698530, 2020). "Twenty-four hours following infection, we stained the mock-infected and the infected cells for the expression of NKG2D ligands: MICA, MICB, ULBP1, ULBP2, ULBP3, and ULBP4." (PMID 32698530, 2020). "While ULBP-1, ULBP-2/5/6, and ULBP-3 are rarely expressed on healthy primary CD4+ T cells, it is well established that infection with several laboratory strains of HIV can induce their surface expression." (PMID 29023371, 2017). "In contrast, at 72 hours post infection, the mRNA levels of ULBP1 were substantially reduced, while the ULBP2 and ULBP3 mRNA levels remained unchanged." (PMID 26992229, 2016). "Shedding of MICA, ULBP2, and ULBP3 was not enhanced post-infection, whereas shedding of MICB was reduced." (PMID 37753084, 2023). "Since ULBP3 is not expressed on HSB-2 cells, we overexpressed this ligand in HSB-2 cells and confirmed its loss after infection with HHV-6A (“ULBP3-HIS”)." (PMID 34721381, 2021).
ULBP3 also shares sentences with these, for which no sentence is quoted: HCMV infection (2 papers); ovarian carcinoma (2); alopecia areata (1); cervical intraepithelial neoplasia (1); chronic myeloid leukemia (1); endometriosis (1); esophageal carcinoma (1); gastric cancer (1); hepatocellular carcinoma (1); Hodgkins lymphoma (1); immune diseases (1); leukemia (1); myelodysplastic syndrome (1); nasopharyngeal carcinoma (1); non-small cell lung carcinoma (1); ovarian tumors (1); primary sclerosing cholangitis (1); rheumatoid arthritis (1); systemic lupus erythematosus (1); vitiligo (1).